TRAF6 (TNF receptor associated factor 6)
Diseases named in the same sentence as TRAF6 in open-access papers (continued):
Sharing a sentence is not in itself a finding about the gene and the disease.
tumor (continued). "Notably, CCL3 exemplifies the dual role of cytokines in CRC progression: while it recruits immune cells via chemotaxis, its overexpression activates the TRAF6/NF-κB axis to promote tumor cell survival and invasion." (PMID 40963625, 2025). "Conversely, CCL3 overexpression enhanced TRAF6 and NF-κB levels and drove increased tumor growth." (PMID 41153795, 2025). "Therefore, CMNPD12791-8 holds promise as a potential inhibitor of TRAF6 for inhibiting tumor growth and metastasis." (PMID 38921571, 2024). "Similarly, TRAF-6, gene expression showed a statistically significant increase in the tumor-bearing group compared to control (p < 0.01)." (PMID 39394174, 2024). "Consequently, the significant involvement of TRAF6 in maintaining immune system homeostasis and affecting tumor immunity necessitates further investigation." (PMID 38169510, 2024). "TRAF6 is considered as a promising target for the development of anti-tumor drugs." (PMID 38921571, 2024). "Both NIK and TRAF6 interact directly with some receptors through an intermediate protein, leading to the activation of the immune response, such as dendritic cells (DCs) and naïve T cells, and supporting the tumor progression." (PMID 39200219, 2024). "Consequently, the increased level of TRAF6 in tumor cells significantly contributes to cancer promotion by activating the downstream NF-κB signaling cascade via the classical pathway." (PMID 38169510, 2024). "Although increasing studies have highlighted the role of TRAF6 in tumor regulation, the specific ubiquitination mechanism of TRAF6 in chemoresistant tumor cells remains unclear." (PMID 39706834, 2024). "Among them, TRAF6, a ubiquitin ligase, possesses unique receptor binding specificity and shows diverse functions in immune system regulation, cellular signaling, central nervous system, and tumor formation." (PMID 38004473, 2023). "Various mechanisms have been described, one of them involving the inhibition of the TNF receptor-associated factor 6 (TRAF6)/NF-κB pathway by bLF in tumor endothelial cells but not in nontumor endothelial cells." (PMID 37111542, 2023). "Additionally, the overexpression of TRAF6 was found to promote tumor EMT and enhance the expression of PCNA." (PMID 38062041, 2023). "All this indicates that since TRAF6 regulation could facilitate the modulation of tumor progression of various types, much importance should be attached to the exploration of its exact impact on TNBC chemoresistance." (PMID 37746908, 2023). "Moreover, TRAF6 has been shown to facilitate tumor proliferation, invasion, and metastasis in multiple types of cancer." (PMID 37746908, 2023). "Importantly, Treg-specific TRAF6 depleted cells attenuated tumor size and boosted anti-tumor immunity." (PMID 37936703, 2023). "Moreover, pUL48, a tegument protein of HCMV, can encode DUB for the deubiquitination of TRAF6, TRAF3, IRAK1, IRF7 and STING, thereby inhibiting type I IFN responses, obtaining tumor precursor function, and promoting tumor formation." (PMID 37600809, 2023). "TRAF6 interacts with and catalyzes K63-linked ubiquitination of PRMT5, which in turn promotes PRMT5-MEP50 complex formation, activation, cell proliferation, and tumor growth." (PMID 37173967, 2023). "Hence, bLF specifically suppressed tumor angiogenesis through p-p65 inhibition by binding to TRAF6 and suppressing HIF-1α activation followed by VEGF/VEGFR down-regulation." (PMID 36678795, 2023). "TRAF6 is highly expressed in MDSCs from both lung cancer patients and tumor-bearing mice." (PMID 36439186, 2022). "Knockdown of p62 resulted in reduced colony formation or tumor growth and reduced TRAF6 activation and NF-κB nuclear localization both in vitro and in vivo, thus indicating that p62 sustains NF-κB activation and leukemic cell functions (i.e., cell cycle and myeloid cell development) through TRAF6." (PMID 35884618, 2022). "TRAF6 is also involved in tumor development, invasion, and metastasis." (PMID 35240920, 2022).
tumor (continued). "TRAF6 can activate NF-κB in the nucleus through the classical pathway or the alternative pathway and produce biological effects to participate in the process of inflammation and tumor invasion and metastasis." (PMID 35935327, 2022). "TRAF6 was found to be overexpressed in primary NSCLC tumor tissue and all tested cell lines." (PMID 34409101, 2021). "Moreover, silencing of TRAF6 remarkably decreased the levels of phosphorylated STAT3 in MDSCs from tumor tissue of TB mice." (PMID 33717204, 2021). "Moreover, knockdown of TRAF6 attenuated the ability of MDSCs to accelerate tumor progression in tumor-bearing mice." (PMID 33717204, 2021). "Flow cytometry analysis of tumor infiltrating leukocytes revealed an increased presence of inflammatory monocytes (Ly6Chi), and reduced numbers of myeloid cells (CD11b+) and tumor-associated macrophages; TAMs (CD11b+CD64+CD11c+) in TRAF6-KD tumors." (PMID 33142239, 2020). "Therefore, CYLD is considered a tumor suppressor, and its dysfunction leads to excessive activation of TRAF6, resulting in a series of pathological responses." (PMID 32905356, 2020). "Importantly, the final rescue experiments testified that LOXL1-AS1 facilitated in vitro and in vivo tumor growth by targeting miR-589-5p/TRAF6 pathway in laryngocarcinoma." (PMID 33061856, 2020). "TRAF6-KD tumors showed an increased detection of apoptotic cells, as determined by cleaved-caspase 3 staining, when compared to Mock tumors, which correlates with reduced tumor size." (PMID 33142239, 2020). "TRAF6 is related to the proliferation, invasion, migration, and apoptosis of tumor cells." (PMID 33294443, 2020). "Besides, miR-589-5p worked as a tumor-inhibitor while TRAF6 functioned as a tumor-facilitator in laryngocarcinoma." (PMID 33061856, 2020). "Previously, TRAF6 overexpression in tumor cells had been shown to stabilize HIF-1α." (PMID 33142239, 2020). "Down-regulation of TRAF6 resulted in virtual abrogation of orthotopic tumor growth." (PMID 33142239, 2020). "When we analyzed the polarization of macrophages into protumorigenic M2 or antitumorigenic M1 one using the CD206 and MHCII markers, respectively, increased numbers of M1 type macrophages in TRAF6-KD were observed, which is in agreement with the observed tumor size reduction." (PMID 33142239, 2020). "Next, we determined the effect of miR-146b-5p and TRAF6 on the tumor growth in vitro." (PMID 30643010, 2019). "Additionally, deficiencies in Treg TRAF6 expression lead to reduced FOXP3+ T‐cell frequencies within the CD4+ T cells infiltrating several lymphoid and tumor tissues." (PMID 30886050, 2019). "In OS cells, silencing of TRAF6 mimicked the anti-tumor effects of miR-146b-5p." (PMID 30643010, 2019). "Moreover, the role of Th9 cells in eradicating advance tumor were also identified and suggested that IL-9, Eomes, and Traf6 of Th9 cells are essential in eradicating advance tumor." (PMID 31164892, 2019). "We performed a comprehensive immunohistochemical analysis of TRAF6 expression in SCCHN tumours." (PMID 29193723, 2018). "We next evaluated the anti-tumor growth effect of TRAF6 shRNAs in vivo." (PMID 29703234, 2018). "Interestingly, the importance of TRAF6-dependent oncogenic pathways in human cancers is also underscored by the findings that TRAF6 mRNA is the direct target of tumor suppressive mi-RNAs, including miR-146a, and miR-141-3p." (PMID 30294322, 2018). "Besides, TRAF6 and Ube2N protein levels were notably lower in tumor cell lines than in PHK confirming the results from gene expression analysis for HPV positive cell lines." (PMID 29472602, 2018). "Some researchers have found that TRAF6 is closely related to tumor development." (PMID 28592924, 2017).
tumor (continued). "Furthermore, HCMV deubiquitinase acquires pro-tumor functions by inhibiting PRR-mediated type I interferon via deubiquitination of TRAF6, TRAF3, IRAK1, IRF7 and STING." (PMID 28981114, 2017). "In addition, PSP were also evaluated for its activation of TLR4, TLR4-downstream molecules (TRAF6, NF-κB and AP-1) in spleens of tumor-bearing C57BL/10J (TLR4+/+) and C57BL/10ScCr (TLR4-/-) mice." (PMID 26032186, 2015). "Our data indicate that IL-1β enhances the pro-inflammatory response by suppressing TGF-βsignaling through TRAF6-mediated sequestration of TβRIII, which may be an important contributor to the early stages of tumor progression." (PMID 22427868, 2012). "Interestingly, the protein kinase AKT - activated and transmitting survival signals in many tumours - has also been reported to be an ubiquitination target of TRAF6." (PMID 21034493, 2010). "For example, miR-146a attenuates pro-inflammatory signaling by directly targeting IRAK1 and TRAF6, key adapters in TLR/NF-κB pathways—mechanistically linked to reduced secretion of IL-6 and TNF-α in epithelial and myeloid systems, a paradigm broadly applicable to tumor contexts." (PMID 41226828, 2025). "Specifically, tumor cells induced secretion of CCL2 (C-C motif chemokine ligand 2), leading to macrophage activation and subsequent TWEAK secretion by tumor cells via the CCL5/TRAF6 (TNF receptor-associated factor 6)/NF-κB signaling axis, which stimulated muscular atrophy." (PMID 40427186, 2025). "In PCa cells, RES was found to block tumor invasion and migration by increasing the expression of TIMP2/3 and eleven translocation 1 (TET1) levels while simultaneously reducing the expression of MMP2/9 and TNF Receptor-associated factor 6 decreases (TRAF6)/NF-B/SLUG axis." (PMID 40143065, 2025). "This suggests that targeting TRAF6 could be an effective strategy for inhibiting tumor growth." (PMID 38921571, 2024). "Thus, TRAF6 appears to be a key regulator of autophagy-promoting tumor metastasis." (PMID 38135696, 2024). "However, it is unclear whether SPHK1 relies on TRAF6 to induce autophagy and thus promote tumor metastasis in CRC." (PMID 38135696, 2024). "Another study showed that the transcriptional activity of TRAF6 is regulated by miR146b-5p, and that inhibition of miR146b-5p can increase inflammatory cytokine secretion and TRAF6 expression in renal tumor mouse models, further inhibiting orthotropic tumor cell growth." (PMID 37847185, 2023). "MAPKs were also reported to be classical signaling pathways mediated by TRAF6 in tumor progression, ultimately leading to the activation of NF‐κB and AP‐110, 35; however, whether TRAF6 performs some other regulatory mechanisms that can contribute to chemoresistance is still worth being explored." (PMID 37746908, 2023). "Notably, TNF receptor-associated factor 6 (TRAF6), a member of TRAF protein family that transduced signals from TNF receptors, inhibits HIF-1 polyubiquitination-mediated degradation and thus promotes tumor angiogenesis." (PMID 34629100, 2021). "Thus, we hypothesized that the strong suppressive activity of MDSCs from tumor tissues may be attributed to the high expression of TRAF6." (PMID 33717204, 2021). "Interestingly, TRAF6-KD tumor showed also increased number of Ki67-positive tumor cells." (PMID 33142239, 2020). "Similarly, the TRAF6 inhibitor decreases the population of intratumor Tregs by impeding the migration of Tregs towards the tumor, thus enhancing T cell-mediated antitumor immunity and thereby inhibiting the growth of Hepa1-6 tumor in immunocompetent mice, but not in immunodeficient mice." (PMID 33294443, 2020). "While several inflammatory mediators (IL-6, TNF-α, TWEAK, TRAF6, INF-γ, and LIF) have been implicated as drivers of cancer-associated wasting, very little is known about their origin, whether skeletal muscle, immune cell, or tumor-derived." (PMID 32982782, 2020).
tumor (continued). "Knockout of TRAF6 in otherwise sensitive models abrogated DNMT degradation and tumor suppressor reactivation, thereby confirming its role as a gatekeeper of DAC efficacy." (PMID 41008798, 2025). "While sensitive models exhibited durable tumor suppression and DNMT degradation via TRAF6-mediated ubiquitination, resistant models maintained DNMT expression and showed rapid regrowth post-treatment." (PMID 41008798, 2025). "Specifically, miR‐146a‐5p has been reported to bind directly to WNT2, EGFR, NOTCH2, TRAF6, IRAK1 and EIF5A2 to inhibit EMT and act as a tumour suppressor in various human cancers." (PMID 40785027, 2025). "TRAF6 recruits and activates TAK1 and IKK to stimulate NF-kappa B and MAPK signaling pathways, enhancing inflammation and tumor cell survival." (PMID 41465470, 2025). "Mitoxantrone effectively decreased the levels of both EGFR and TRAF6 in CRC cell lines, leading to significant reductions in cell proliferation and tumor spheroid formation." (PMID 41419456, 2025). "Acts by inhibit TRAF6 e MAPK11 and the NF-κB and MAPK pathways reducing inflammation induced apoptosis of tumor cells." (PMID 41465470, 2025). "Restoring miR-146a or pharmacologically inhibiting its targets (TRAF6, RIPK2) reverses these pathological changes and prevents tumor development." (PMID 41463227, 2025). "TRAF6 influences cancer signaling pathways, particularly the NF-κB pathway and MAPK pathway, thereby controlling tumor cell growth, viability, and invasion." (PMID 38921571, 2024). "A comprehensive understanding of the role of TRAF6 in HCC pathogenesis and tumor progression is crucial for the development of effective treatment modalities for HCC." (PMID 38169510, 2024). "We found that macrophages in the tumor-containing lymph nodes expressed significantly higher levels of TLR3 and TRAF6 compared to those in the tumor-free lymph nodes." (PMID 38719996, 2024). "A previously reported study revealed that TRAF6 regulated the PI3K/AKT signal pathway, resulting in the phosphorylation and ubiquitination of AKT and promoting tumor cell growth and proliferation." (PMID 37746908, 2023). "Previous studies reported that in other tumor types, UBE2O mediates the degradation of AMPKα2 and TRAF6, thus affecting the AMPK and NFKB pathways, respectively, as well as EMT, DNA repair, and lipid metabolism." (PMID 38129382, 2023). "We then performed subcutaneous MOCK(TRAF6), MOCK(WT), MOCK(RIPK3−/−) and MOCK (MLKL−/−) group of cell transplantation tumor models through RIPK3−/− and MLKL−/− mice of C57BL/6 genetic background." (PMID 36604411, 2023). "It will be worth investigating how TRAF6 and PRMT5 coordinatively control these signaling pathways to regulate various biological processes, cell proliferation, migration, and tumor growth." (PMID 37173967, 2023). "Our investigation shows that TRAF6 as well as TRAF4 genes are highly amplified in samples from metastatic breast cancer patients (TRAF6: 9.3% and TRAF4: 27.8%) when compared primary tumours (TRAF6: 7.2% and TRAF4: 21.7%)." (PMID 36944688, 2023). "TRAF members particularly TRAF6 are known key regulators of tumour‐promoting inflammation and immune response along TLR–NF‐κB pathway, therefore, small molecule inhibitors of TRAF6‐induced NF‐κB activating inflammation have been identified." (PMID 36881608, 2023). "Tissue immunofluorescence assay also confirmed that TRAF6 was correlated with the expressions of PKM2 and Bcl‐2 in chemoresistant TNBC patients, which shared the same location in TNBC tumor tissues." (PMID 37746908, 2023).
tumor (continued). "To further verify the regulatory relationship between TRAF6 and the RIPK1-RIPK3-MLKL signaling axis, we performed a subcutaneous transplantation tumor model of high TRAF6 expressing cells through RIPK3−/− and MLKL−/− mice of C57BL/6 genetic background." (PMID 36604411, 2023). "It was reported that TRAF6 binds to HIF-1α and increases HIF-1α polyubiquitination, promoting in vivo tumor angiogenesis." (PMID 36678795, 2023). "Our results above suggested that USP8 regulated the efficacy of anti-PD-1/PD-L1 immunotherapy largely through two arms: the TRAF6-PD-L1 axis and the TRAF6-NF-κB-MHC-I pathway, to shape the tumor microenvironment." (PMID 35361799, 2022). "The inhibition of TRAF6, while decreasing EGFR and other signaling pathway, halts tumor cell growth and therefore has a huge therapeutic potential." (PMID 35956111, 2022). "However, the role of TRAF6 played in tumor glycolysis was largely unknown." (PMID 34409101, 2021). "By mediating Akt ubiquitination, TRAF6 promoted Akt activation and enhanced HIF-1 mediated transcription of hexokinase-2, giving rise to the increase of tumor glycolysis in NSCLC." (PMID 34409101, 2021). "In the tumor-bearing animals, treatment with WFA led to a statistically significant dose-dependent transcriptional downregulation of Fbxo30, Fbxo32, Trim63, and Traf6 compared to the tumor-bearing vehicle-treated group (p < 0.0001 for all comparisons)." (PMID 33718372, 2021). "With the knockdown of TRAF6 in NSCLC, we examined the effect of shTRAF6 on tumor glycolysis by measuring the glucose uptake and lactate production." (PMID 34409101, 2021). "Thus, we asked whether TRAF6-KD affected tumor angiogenesis." (PMID 33142239, 2020). "We revealed that circ_0001955, TRAF6 and MAPK11 levels were increased, while miR-516a-5p levels were decreased in HCC tumor tissues compared to adjacent normal tissues." (PMID 31822654, 2019). "The expression of TRAF6 protein was upregulated in OSCC cell lines and clinical tumor tissue samples." (PMID 29703234, 2018). "Using the TRAF6 knockdown SAS cancer xenograft model system, we were able to demonstrate a decreased tumor growth rate and decreased TRAF6 protein expression in the cancer xenografts when compared with parental SAS cancer xenografts." (PMID 29703234, 2018). "In general, our results indicate that miR-146b-5p inhibits tumor growth and metastasis of HCC by targeting TRAF6 mediated Akt phosphorylation." (PMID 28404923, 2017). "TRAF6 overexpression in NIH3T3 cells promoted anchorage-independent growth and tumor formation via activating NF-κB signaling." (PMID 29202848, 2017). "APS and LPS were found to significantly induce the expressions of mRNAs and proteins of TLR4, TRAF-6, NF-κB and AP-1 in the TLR4+/+ tumor-bearing mice, compared with those in the NS group (P < 0.05)." (PMID 28303957, 2017). "Inversely, there was no remarkable differences in the expression of mRNA and proteins of TLR4, TRAF-6, NF-κB and AP-1 among groups in the TLR4−/− tumor-bearing mice (P > 0.05)." (PMID 28303957, 2017). "For example, miR-146a down-regulates the expression of TRAF6 and IRAK1 to suppress the activity of the NF-κB signaling pathway and has a key role in suppressing tumorigenesis and tumor progression by inhibiting tumor cell migration and invasion." (PMID 27683641, 2016). "From the results, we found that the mRNA and protein levels of TLR4, TRAF6, NF-κB and AP-1 were significantly upregulated by PSP as well as LPS in spleens of B10 (TLR4+/+) tumor-bearing mice." (PMID 26032186, 2015). "In vivo, the activation of TLR4 and TLR4-downstream molecules (TRAF6, NF-κB and AP-1) in spleens of B10 (TLR4+/+) and ScCr (TLR4−/−) tumor-bearing mice were measured by Q-PCR and Western blot." (PMID 26032186, 2015).